RET (ret proto-oncogene)
Diseases named in the same sentence as RET in open-access papers (continued):
Sharing a sentence is not in itself a finding about the gene and the disease.
tumor (continued). "Sorafenib is a multikinase inhibitor that targets the Raf/MAPK/ERK signaling pathway, interfering with the tyrosine kinases VEGFR-2/3, PDGFR-β, B-Raf, c-Raf, FGFR1, Flt3, c-KIT, RET, and p38 α, and induces tumor cell apoptosis in HCC." (PMID 33808407, 2021). "Note that in our series, the only tumor with distant metastasis to the lung in a 12-year-old boy harbored RET/PTC3." (PMID 34282777, 2021). "Vandetanib has been found to be effective in inducing in vivo tumor regression in TNBC PDX models with high expression of RET or EGFR with concordant suppression of RET/EGFR phosphorylation and MEK/ERK pathway activation." (PMID 34207383, 2021). "The rate of missing tumor response data was 41.3 and 58.7%, 11.1 and 34.4%, and 39.1 and 49.3% for the RET+ and RET- cohort, respectively for the first-line, first-line pembro + PC, and second-line settings." (PMID 33402119, 2021). "This approval was based on a single-arm phase I/II trial, LIBRETTO-001, which demonstrated overall tumor response rates of 85 and 64% for patients with RET-fusion positive NSCLC who were treatment naïve and previously treated, respectively." (PMID 33402119, 2021). "Sunitinib, a MKI targeting VEGFR1,2,3, Kit, PDGFRA/B, FLT-3 and RET has also shown efficacy in the reduction of the primary tumor proliferation and the tumor vasculature in cell-derived osteosarcoma mouse models." (PMID 34069999, 2021). "Most probably, the correlations with tumor aggressiveness for all tumors harboring any type of RET/PTC were also due to RET/PTC3." (PMID 34282777, 2021). "This study describes the characterization of the indirubin-3′-oxime compound LDD-2633 as a potent and novel RET inhibitor with in vitro and in vivo anti-tumor functions." (PMID 33419162, 2021). "In NIH3T3 NCOA4-RET tumours, 0.3, 1 and 3 mg/kg doses were all able to inhibit RET up to 12 h, with RET phosphorylation being partially restored after 24 h." (PMID 34373541, 2021). "A total of 42 somatic hot spot mutations were detected in tumor tissue DNA, and 39 mutations were detected in CTC-DNA, all of which included common changes in PTEN, MET, EGFR, RET, and FGFR3." (PMID 34178679, 2021). "The carcinogenesis can also be promoted indirectly through GFL-GFRα-RET-dependent modulation of the tumor microenvironment what makes this signaling a potentially valuable molecular target for cancer therapy." (PMID 34149933, 2021). "Introduction of the RET mutants into human EOC cells increases RET signaling, cell viability, anchorage-independent cell growth and tumor xenograft growth in nude mice, demonstrating that they are activating mutations." (PMID 32293499, 2020). "Potential examples of such tumor-agnostic targets other than NTRK include (but not limited to) ALK, BRAF, BRCAness, FGFR, HER2, HER3, homologous recombination deficiency (HRD), KRAS, RET, ROS1, tumor mutation burden (TMB) high." (PMID 31974683, 2020). "Fortunately, the selective RET inhibitors selpercatinib and pralsetinib have demonstrated more substantial anti-tumor activity in NSCLC patients harboring RET rearrangements." (PMID 33182254, 2020). "PRKAR1A, one of the RET fusion partners, is the tumor suppressor protein involved in inheritance of Carney complex, a tumor-prone syndrome." (PMID 32326537, 2020). "With the wide use of multi-gene panel testing, rare genetic alterations such as RET or tropomyosin receptor kinase (TRK) fusions are increasingly identified in a variety of tumour types including CCA." (PMID 32932925, 2020). "In the SU cohort, positive RET staining of tumor cells was noted in only 7 HPV-positive and 1 HPV-negative patients." (PMID 32084217, 2020). "In a study of more than 10,000 cases from 33 cancer types, high tumor expression of a germline variant in an oncogene (AR, MET, RET, CBL, and PTPN11) was found in 33 patients." (PMID 32295625, 2020). "Previously, it was reported that the GDNF/GFRα/RET system is involved in tumor cell proliferation, invasion and migration." (PMID 32438692, 2020).
tumor (continued). "The RAS/MAPK and PI3/AKT signaling pathways are enabled due to RET proto-oncogene activation or NF1 tumor suppressor inactivation, resulting in tumor formation." (PMID 33081307, 2020). "Several patients experienced clinical benefit with tumor mutations in cKIT, CSF-1R, PDGFRα, PDGFRβ, VEGFR1, VEGFR2, FLT3, FGFR2, RET, and TrkA." (PMID 32292573, 2020). "By employing proteogenomic analysis of matching normal vs tumor vs lymph node metastasis of the same patient, we identified and validated a novel oncogenic RET fusion as well as other druggable targets in PTCs." (PMID 32345963, 2020). "By performing genomic analysis of a single PTC patient, we identified a novel, oncogenic RET fusion in both tumor and LN metastatic lesions, whose expression readily transformed immortalized human thyroid cells and induced tumor formation in mice." (PMID 32345963, 2020). "Some of the tumor tissues reported in this study had been already characterized for driving lesions such as BRAFV600E and H/N/KRAS mutations, as well as RET and TRK gene fusions." (PMID 31906302, 2020). "We first evaluated the radiologic features of the primary tumor in RET+ NSCLC compared to ALK+ or ROS1+ NSCLC." (PMID 32183422, 2020). "A recent analysis of 181 sMTC showed that RAS-mutant tumors had better outcome and a lower tumor staging than RET-mutant tumors." (PMID 32668761, 2020). "Its expression is increased in tumor tissues of patients and involved in the following pathways RET signaling and G-protein signaling_RhoA regulation." (PMID 32193399, 2020). "We have shown that recovered CTCs from selected patients with ROS1, ALK, and RET rearrangements carried genomic aberrations matching the primary tumor." (PMID 31947893, 2020). "Although outside of the scope of this review, RET fusions have also been identified in ~20% of papillary thyroid carcinomas, and at a lower frequency (≤1%) in other tumor types including breast, colorectal, and pancreatic cancers." (PMID 33553195, 2020). "More recently, the advent of highly sensitive massive parallel (next generation sequencing, NGS) sequencing of tumor DNA or cell-free (cfDNA) circulating tumor DNA, allowed for the detection of RET fusions in many other solid and hematopoietic malignancies." (PMID 32326537, 2020). "Regorafenib inhibits vascular endothelial growth factor receptors (VEGFRs) to reduce the degree of islet cell inflammation and the mutant oncogenic kinases KIT, B-RAF, and RET to inhibit tumor angiogenesis and tumor cell proliferation." (PMID 32660121, 2020). "In patient-derived tumor cells (PDCs) with nuclear receptor coactivator 4 (NCOA4)-RET fusion obtained from the brain metastasis of a 63-year-old mCRC patient, vandetanib revealed a significant antitumor effect in terms of cell viability to CRC-PDCs." (PMID 32413973, 2020). "In vitro RET-BDP-TNM showed higher fluorescence intensity than RETBDP-NNM because of the folic acid ligand at the tumor site." (PMID 32641993, 2020). "We report an adult patient with ATC and a biopsied tumor metastasis harboring a CCDC6-RET gene fusion who responded dramatically to LOXO-292, a highly selective RET inhibitor currently in clinical development." (PMID 32292131, 2020). "In the analysis of large databases (more than 60,000 tumor samples), RET fusions were found in 13/560 (2.32%) and 36/500 (7.2 %) PTC cases, 1/107 (0.93%) ATC cases, and 6/134 (4.47%) PDTC cases." (PMID 32326537, 2020). "The RET/PTC3 rearrangement, mostly found in tumors from patients with prior radiation exposure, is associated with aggressive features such as larger tumor size, extrathyroidal extension, and nodal metastases." (PMID 30552739, 2019). "Other variants detected in this tumor, such as those inFGFR3,PDGFRA,KDR (c.1416A>T),CSF1R,EGFR,RET,HRAS,PIK3CA,FLT3 (c.1310-3T>C), andSMAD4, are benign." (PMID 32612806, 2019).
tumor (continued). "The REarranged during Transfection (RET) gene encodes a receptor tyrosine kinase that is a known oncoprotein, with oncogenic mutations identified in multiple tumor types." (PMID 31695841, 2019). "Consistent with this, silencing of RET dramatically reduced the highly elevated tumor growth and metastatic ability of lamin B1–depleted cells." (PMID 31015297, 2019). "GDNF was demonstrated to promote the proliferation and invasion of tumor cells through phosphorylating its receptor RET." (PMID 31024838, 2019). "In an assessment of circulating tumor DNA (ctDNA) RET alterations in patients with cancer, 15 of 126 NSCLC patients had co-occurring EGFR mutation and 5 had developed resistance to prior EGFR TKI." (PMID 30915273, 2019). "Lenvatinib is an oral tyrosine kinase inhibitor targeting VEGFR1/2/3, FGFR1/2/3/4, PDGFRα, KIT, and RET to inhibit tumor angiogenesis and growth." (PMID 30889843, 2019). "These fusions were both confirmed to be tumour-specific and preserved the tyrosine kinase domain in the 3′ fusion partners RET and NTRK1, respectively." (PMID 31653970, 2019). "By expressing RET, the tumour cells develop de novo resistance and become resistant after an initial response." (PMID 30621641, 2019). "The parental RET gene (1498 bp band) was present in both tumor and blood samples, while the retrocopy band (238 bp) was observed only in DNA isolated from MTC samples, indicating that it is a cancer-specific event." (PMID 31288802, 2019). "RET mutations in MTC demonstrate distinctive mutational heterogeneity and the mutational status can differ between primary tumor and other lesions and even among synchronous or metachronous metastases." (PMID 30206772, 2019). "A tissue microarray (TMA) was constructed from tumor specimens in triplicate and stained by immunohistochemistry for RET, phospho‐MEK, MAPK(dpERK), PPARγ, and phospho‐AKT(pAKT)." (PMID 30552739, 2019). "In this study, patients with RET positive tumor staining alone were half as likely to experience recurrence compared to patients with RET‐negative tumors." (PMID 30552739, 2019). "We observed differences in RET tumor staining between adult and pediatric patients, and differences in BRAF V600E mutation between ATA risk groups." (PMID 30552739, 2019). "The parental RET copy was present in both tumor and blood samples, while the RET retrocopy was MTC-specific." (PMID 31288802, 2019). "Tumor diameters were significantly smaller in the SDHx subgroup (3.9 cm) and significantly higher in the RET subgroup (7.2 cm) compared to cases with other genetic backgrounds." (PMID 31142060, 2019). "Forty-four unique fusions were identified in 40 (1.1%) of the 3,808 patients with circulating tumor DNA detected: RET (n = 6; 36% of all fusions detected), FGFR3 (n = 2; 27%), ALK (n = 10, 23%), NTRK1 (n = 3; 7%), ROS1 (n = 2; 5%), and FGFR2 (n = 1; 2%)." (PMID 33015522, 2019). "Tumor protein was verified for the expression of RET fusions by immunoblot and activation of PI3K-AKT and MAPK pathways was observed." (PMID 30446652, 2018). "In the other 75% of cases, MTC is a sporadic tumor, and with exception of RAS alterations that have been found in approximately 10% of cases, somatic mutations in the RET proto-oncogene appear to be the most common genetic alteration in MTC tumorigenesis." (PMID 29515777, 2018). "Vandetanib and Nintedanib antagonize RET signaling, block tumor development but exhibit different anti-proliferative effects on tumor cells." (PMID 30701022, 2018). "Sunitinib is an oral, multitargeted TKI targeting VEGFR, Kit, platelet-derived growth factor (PDGFR), FMS-like tyrosine kinase 3 (FLT3) and RET on tumor cells, tumor neovasculature and pericytes." (PMID 30680072, 2018). "The depletion of prp8 efficiently blocked Ras-, EGFR- and Notch-driven tumours but, in contrast, enhanced tumours that were driven by oncogenic RET, suggesting a context-specific role in hyperplasia." (PMID 30333215, 2018).
tumor (continued). "As such, GFL RET signaling is an important target for novel therapeutic approaches to limit tumor growth and spread and improve disease outcomes." (PMID 30666215, 2018). "Based on experiments described in NIH/3T3 cells, NCOA4-RET was observed to be the fastest growing cell line and this translated to tumor formation in less than 2 weeks; whereas ΔRET and RETamp were slower in comparison, taking longer than a month." (PMID 30446652, 2018). "Overall, results indicated that all three RET alterations are sensitive to cabozantinib as evidenced by significant tumor volume reduction." (PMID 30446652, 2018). "Immunohistochemistry revealed positive staining for the proliferation marker Ki-67 for RETamp, ΔRET, and NCOA4-RET tumor tissues." (PMID 30446652, 2018). "In response to GFLs, which are released at some level by many tumors as well as by many cell types in the tumor microenvironment, RET signaling can enhance growth, promote tumor spread or even affect response to therapies." (PMID 30666215, 2018). "These patients were informed about the hereditary origins of their neoplasms, and RET genetic screening was subsequently offered to their relatives." (PMID 30624503, 2018). "In many of these diseases, RET appears to stimulate tumor cell migration or invasion and is correlated with reduced overall survival." (PMID 30666215, 2018). "In the tumour cells a reduction of mitotic index and of RET phosphorylation and signalling have been observed." (PMID 30423915, 2018). "Upregulation of RET and GDNF is associated with increased expression of matrix degrading metalloproteinases that facilitate the invasion of tumor cells into the perineural space." (PMID 30666215, 2018). "Together, these data reveal a complex web of autocrine and paracrine stimulatory signals that promote remodeling of the tumor environment, facilitating the oncogenic potential of RET-expressing tumors." (PMID 30666215, 2018). "The expression of GDNF (by glia or fibroblasts), and its cognate receptor RET, in organoids and the parental tumor implies crosstalk between glia and tumor cells." (PMID 30353124, 2018). "We also observed that relatives who had a diagnosis of MTC after RET screening had smaller tumor dimensions than index patients, but the degree of lymph node involvement was similar between the two groups." (PMID 30624503, 2018). "Another multi-kinase inhibitor sunitinib, an anti-PDGFRα/β, VEGFR1/2/3, KIT, FLT3, CSF- b1R and RET, has been shown to decrease primary tumor proliferation and reduce tumor vasculature in cell-derived intratibial OS model in SCID mice." (PMID 29520051, 2018). "Next, the effect of RET inhibitor, cabozantinib on tumor response was tested in each xenograft model." (PMID 30446652, 2018). "Consistent with the dose-dependent anti-tumor activity of ponatinib, corresponding inhibition of p-RET in tumors in vivo was also observed 6 hours post treatment." (PMID 30038711, 2018). "Over 30 RET fusion partner genes have been identified to date, and the distribution of different partners varies amongst tumor types." (PMID 30666215, 2018). "This pathology-defined prognosis is also dependent on both tumor stage and the status of genetic mutations in the EGFR, KRAS, ALK, RET, and BRAF genes." (PMID 29137260, 2017). "The distribution of RET/PTC rearrangements within this tumor is quite heterogeneous, and varies from the involvement of almost all neoplastic cells to presence in only a small fraction of the tumor cells." (PMID 28417935, 2017). "Both the cell lines KTC-1 and TPC-1 harbor mutations (RET/PTC1 and BRAFV600E, respectively) that upregulate MAPK/ERK signaling transductions associated with promoting tumor migration and metastases." (PMID 28498808, 2017). "M1 contains tumours with SDHx mutations and hypermethylation, M2 VHL-mutated tumours, and M3 tumours with NF1 and RET mutations and hypomethylation." (PMID 28327598, 2017).
tumor (continued). "We further demonstrated that this pathology-determined OS can be affected by both tumor stage and status of oncogenic mutations in EGFR, KRAS, ALK, RET, and BRAF genes." (PMID 29137260, 2017). "Small molecule inhibitor regorafenib has been suggested to be a novel RET inhibitor in vitro, and it exhibits anti-tumor effects in various cancer types." (PMID 29262623, 2017). "Next, we tested cabozantinib (CB), a TKI that targets VEGF receptors (VEGFRs), MET, AXL, TIE-2, RET and other RTKs involved in tumor development and progression through angiogenesis, invasiveness, metastasis, anti-apoptosis and drug resistance." (PMID 29206199, 2017). "The question that then remained to be answered was how miR-182 is connected to activated RET signaling and tumor aggressiveness." (PMID 28122586, 2017). "In the present study, we investigated the effect of alectinib on NCOA4-RET utilizing native tumor cells with this type of RET fusion." (PMID 29088743, 2017). "Other RET inhibitors, sorafenib and sunitinib demonstrated anti-tumor effects on KIF5B-RET transformed cells." (PMID 29262623, 2017). "The median tumour cell RET cytoplasmic and nuclear immunostaining in all ccRCC were 110% and 80%, respectively." (PMID 27092013, 2016). "The most effective inhibitor identified, NVP-AST487, suppressed GDNF-stimulated RET downstream signaling and 3D tumor spheroid growth." (PMID 27602955, 2016). "The decrease in RET protein levels induced by NVP-AST487 treatment was also confirmed at cellular level by immunohistochemistry, indicating that NVP-AST487 was able to access the RET+ cell compartment of the tumor." (PMID 27602955, 2016). "Despite the unquestioned role of RET as an important regulator of tumour pathophysiology, very few attempts have explored its prognostic role in RCC." (PMID 27092013, 2016). "On the other hand, the presence of a RET oncogene somatic mutation in sporadic MTC has been associated with both regional and distant metastases, with a higher mortality and a larger tumor size." (PMID 28018431, 2016). "Although an ALK immunohistochemistry assay has been validated as an effective screening tool, the correlation between RET fusion and RET immunohistochemistry was shown to be relatively low for some tumor types." (PMID 26909603, 2016). "A RET translocation (KIF5B-RET) was first identified by whole genome and transcriptome sequencing of tumor tissue from an adenocarcinoma patient in an advanced stage." (PMID 27528792, 2016). "The significantly mutated cancer-related genes that were identified in tumor tissue included EGFR, KDR, FGFR2, and RET." (PMID 27149458, 2016). "Our data showed that the RET nuclear expression significantly increased not only in metastatic RCC tumours but also in patients with primary tumours, who developed metastasis, compared with patients with renal tumours, who did not develop metastasis." (PMID 27092013, 2016). "One mechanism is to block the signaling pathways by inhibiting kinases, phosphatases, or carboxypeptidases, etc., to stop downstream activation and signaling for tumor growth, for example RET aptamer D4." (PMID 27973403, 2016). "The anti-tumor activity of Apatinib was also evaluated to explore the therapeutic potential in RET fusion–driven LADC." (PMID 27494860, 2016). "We demonstrated the presence of the target in 95% of the tumor samples and 100% of those tumors with an active RET signaling pathway." (PMID 26065416, 2015). "Analysis of the primary tumour suggested that it was driven by the RET oncogene, offering a rationale for treatment with RET inhibitors." (PMID 26404381, 2015). "Tumor tissue with > 15 % split red and green signal in 100 interphase nuclei was defined as positive for the RET fusion gene." (PMID 26268359, 2015). "We evaluated the RET protein expression induced by KIF5B-RET fusion by immunohistochemical analysis of paraffin-embedded tumor tissues with a RET C-peptide monoclonal antibody." (PMID 26268359, 2015).